FBXO46 (F-box protein 46)
Description:
Substrate-recognition component of the SCF(FBXO46) protein ligase complex, which mediates the ubiquitination and degradation of target proteins. In absence of stress, the SCF(FBXO46) complex catalyzes ubiquitination and degradation of MTOR-phosphorylated FBXO31.
Synonyms: FBX46; FBXO34L; 20D7-FC4
Tractability: PROTAC: UniProt records ubiquitination sites on it; ubiquitination databases record sites on it.
Gene: Protein-coding gene on chromosome 19 (45,710,624 to 45,730,919, reverse strand). Ensembl gene ENSG00000177051.
Subcellular location (Human Protein Atlas): Nucleoplasm; Vesicles; Cytosol
Gene Ontology:
Molecular function: protein binding; ubiquitin-like ligase-substrate adaptor activity
Biological process: SCF-dependent proteasomal ubiquitin-dependent protein catabolic process; protein ubiquitination
Cellular component: SCF ubiquitin ligase complex
Genetic constraint (gnomAD): Loss-of-function variants: 13 observed, 30.83 expected, observed/expected ratio (o/e) 0.42, 90% interval 0.27 to 0.67. The synonymous counts are far from expectation, so gnomAD's model fits this gene poorly and the ratio says little. Missense variants: 754 observed, 851.24 expected, observed/expected ratio (o/e) 0.89, 90% interval 0.83 to 0.94. Synonymous variants: 465 observed, 382.2 expected, observed/expected ratio (o/e) 1.22, 90% interval 1.13 to 1.31.
Homologues: Orthologues: chimpanzee FBXO46 (99% identical), macaque FBXO46 (99% identical), dog FBXO46 (96% identical), pig FBXO46 (95% identical), guinea pig FBXO46 (94% identical), mouse Fbxo46 (91% identical), rat Fbxo46 (91% identical), zebrafish fbxo46 (53% identical), tropical clawed frog fbxo46 (42% identical). Paralogues in human: FBXO34 (33% identical).
Diseases named in the same sentence as FBXO46 in open-access papers:
FBXO46 is named in the same sentence as 2 diseases in open-access papers, as found by Europe PMC text mining. Sharing a sentence is not in itself a finding about the gene and the disease. The quoted sentences say what the papers report.
cancer (1 paper, 2019). A tumor composed of atypical neoplastic, often pleomorphic cells that invade other tissues. "FBXO46 plays a role in cancer biogenesis and LRRC59 promotes angiogenesis and can fuel tumor growth." (PMID 31387239, 2019). "Unexpectedly, 3 of the 4 genes are from the gene list with prognostic value in > 6 cancers (YWHAB, MCM4, FBXO46)." (PMID 31387239, 2019). "FBXO46 has not been as thoroughly characterized as the other prognostic genes, but it has been found to be dysregulated in cancer and plays a role in biogenesis of cancer." (PMID 31387239, 2019).
tumor (1 paper, 2019). "Among 17 genes that were included in this panel, the expression of YWHAB, MCM4, LRRC59 and FBXO46 was found to be elevated in tumor tissue compared to normal." (PMID 31387239, 2019).